MIF (macrophage migration inhibitory factor)
Diseases named in the same sentence as MIF in open-access papers (continued):
Sharing a sentence is not in itself a finding about the gene and the disease.
tumor (continued). "While serum biomarker measurement is less invasive than tissue or tumor biopsy, fluctuating serum MIF may prove too difficult to use as a reliable biomarker." (PMID 38730725, 2024). "In addition, MIF can promote tumor cell overexpression of growth mediators and vascular growth factors by activating MAPK signaling pathway." (PMID 38685050, 2024). "With its diverse and tissue-specific functions, MIF may drive additional aspects of tumorigenesis, such as enhancing tumor-promoting inflammation, activating invasion, and deregulating cellular metabolism." (PMID 39233830, 2024). "The results of CellChat analysis revealed an increased output signal of the MIF pathway in mM2-like TAMs, which may contribute to the tumor-promoting property of mM2-like TAMs, while bM2-like TAMs expressed MIF at a relatively low level." (PMID 39507421, 2024). "In addition, SHMT2 is involved in certain processes of tumorigenesis and development and is associated with the expression of MIF, CD74, CXCR4 and CD44 in the HNSCC tumor microenvironment." (PMID 38625586, 2024). "Both the TGF-beta and MIF pathways exhibited notable upregulation in Epi, Endo and Fib cells, indicating their combined impact on cellular growth, matrix alteration, and immune evasion within the tumor environment." (PMID 39468431, 2024). "The recruitment of GrB+ B cells to tumor tissues occurs through the MIF-(CD74 + CXCR4) axis." (PMID 38386050, 2024). "MIF functions as a 3′ flap nuclease, aiding in DNA replication and stimulating tumour growth." (PMID 39187937, 2024). "MIF released from MMP7+ tumour cells activated CD74, CXCR4 and CD44 on immune clusters." (PMID 39187937, 2024). "In the subsequent analysis of the potential pathways between GrB+ B cells and tumor cells, the most important incoming and outgoing L-R pairs were the signaling complexes, macrophage migration inhibitory factor (MIF) -(CD74 + CXCR4) and lymphotoxin-alpha (LTA)–(LTB + LTBR), respectively." (PMID 38386050, 2024). "Key differences involved enhanced communication in BR1 from the tumor cell cluster enriched in immune and cell-cycle-MPs (T2) to reactive microglia states (Mg9, Mg12–13), including upregulation of the microglia-activating MIF_CD74_CD44 axis." (PMID 39372744, 2024). "To further consolidate that the vascular niche and CAFs-derived MIF drives TAMs towards an M1-like polarization via MIF in sGC∆PC tumor, we treated RAW264.7 with ISO-1, a highly specific inhibitor of MIF tautomerase activity, alone or when co-cultured with ECs and pericytes or with CD105neg CAFs." (PMID 38528180, 2024). "Our data corroborates prior reports of MIF and DDT triggering cytokines related to antigen presentation, T cell differentiation and NK cell activity, and tumor-associated macrophage infiltration, particularly expression of M2-type immunosuppressive macrophages." (PMID 39028303, 2024). "Thus, the MIF/CXCR4 signaling axis between tumor cells and macrophages was selected for further investigation." (PMID 39464891, 2024). "mM2-like TAMs were revealed to promote tumor progression by secretion of MIF and SPP1." (PMID 39507421, 2024). "Macrophage migration inhibitory factor (MIF) has been implicated in several of these oncological processes, including driving tumor cell proliferation, inhibiting apoptosis, increasing vascularization, promoting cell migration, and evading immune detection and destruction." (PMID 39233830, 2024). "In C8 and C9 tumor clusters, incoming pattern 1 coordinates signals like MIF, ANGPTL, MK, and PTN." (PMID 38191424, 2024). "An immunomodulatory role of tumor-derived MIF has been reported previously." (PMID 38638429, 2024). "In vivo models demonstrate reduced tumor burden and increased apoptosis with MIF blockade." (PMID 38732068, 2024). "In addition to the L–Rs involved in the MIF pathway, there were many other L–Rs in the PT microenvironment to promote tumor progression, such as SPP1-CD44 of SPP1 pathway." (PMID 38414027, 2024).
tumor (continued). "Furthermore, diminishing MIF expression within the primary tumor in vivo triggers a robust anti-tumor immune response characterized by enhanced DC maturation, followed by an increase in IFN–gamma-producing T cells within the tumor." (PMID 38994937, 2024). "Research on the association between the BM of NSCLC and the MIF/CD74 axis is limited, with only a few studies discovering that MIF is a tumor cell-oriented factors involved in crosstalk between tumor cells and astrocytes and is associated with tumor angiogenesis." (PMID 38685050, 2024). "In this case, it is important to understand whether MIF cycles at the transcript and protein levels in both tumor and healthy tissues, as MIF levels in these tissues could be used as an alternative biomarker of ICB response or irAE development." (PMID 38730725, 2024). "MIF secreted from the tumor cells activates CD74 expressed on DCs." (PMID 39576827, 2024). "However, oxidative conditions typical for the inflammatory microenvironment and tumorous tissues were found to convert MIF into its redox-dependent conformational isoform oxMIF." (PMID 39727487, 2024). "In preclinical studies, first-generation anti-oxMIF antibodies (BaxB01, BaxG03, BaxM159) neutralized some of the key tumor-promoting activities attributed to MIF in vitro and in vivo, and were able to detect oxMIF in primary tumors and metastases of different solid tumors." (PMID 39727487, 2024). "MIF is considered a pro-tumour factor because of its ability to support tumour progression." (PMID 39416730, 2024). "While murine studies have suggested that host-derived MIF drives tumor progression more than tumor-derived MIF, clinical data has correlated high stromal MIF expression with worse survival outcomes and can offer deeper mechanistic insight into its role at the site of tumor development." (PMID 39028303, 2024). "Glutathione peroxidase 4 (GPX4) expression in tumor cells and inhibition of the macrophage migration inhibitory factor (MIF) signaling pathway in the TME may be crucial tactics for synergistic cold tumor immunotherapy for GC." (PMID 38928662, 2024). "Upon MIF/CD74 binding, CD44 is recruited to the receptor complex to initiate Src-family kinase activation, CD44 alternative exon splicing, and expression of tumor-associated isoforms such as CD44v3–v6, which are implicated in enhancing cellular migration, adhesion, and invasion." (PMID 38732068, 2024). "Additionally, the MIF signaling pathway between tumor cells and TAMs or T cells was increased, which has been shown to promote cancer progression." (PMID 38787372, 2024). "In cancer, MIF/CD74 axis is considered to be a signaling pathway that pro-tumor." (PMID 38685050, 2024). "Notably, the cytokine MIF drives oncogenesis by supporting tumor growth, regulating immunological responses, boosting inflammation, and promoting tumor-associated angiogenesis." (PMID 38916819, 2024). "In cancer studies, the MIF indirectly hindered the anti-tumor activity of DCs." (PMID 39202723, 2024). "The findings of this research proposed that serum MIF level may be considered a helpful tumor marker of BC." (PMID 38916819, 2024). "Research on the role of the MIF/CD74 axis in the tumor microenvironment of BM of NSCLC is limited." (PMID 38685050, 2024). "Notably, akin to pericytes in the atherosclerotic vessels, tumor pericytes upregulated MIF expression following sGC deletion, thereby skewing TAM polarization from the M2 to the M1 phenotype." (PMID 38528180, 2024). "In addition to its expression in immune cells, CD74 is overexpressed in various tumor types and can form a complex with MIF, thereby modulating MIF’s function." (PMID 38277205, 2024). "Studies have shown that CD74 promotes tumour cell growth by interacting with MIF." (PMID 36860314, 2023).
tumor (continued). "In cancer, the use of MIF knockdown or knockout cancer cell lines has taught us that, depending on the tumor model used, different immune cells could be affected by MIF-signaling." (PMID 36672343, 2023). "This could be of importance, since MIF was recently positioned as a 3′flap nuclease in charge of regulating DNA replication, having a direct impact on tumor growth." (PMID 36672343, 2023). "In addition, macrophage migration inhibitory factor (MIF) is secreted to bind to CXCR4 on tumor cells to activate the Akt pathway to promote angiogenesis." (PMID 37700840, 2023). "Meanwhile, comparative analysis results between the intercellular communication situation in the HCC microenvironment and that in the non-tumor tissue environment showed that malignant cells communicated more significantly with immune cells through the MIF pathway." (PMID 37842089, 2023). "Macrophages, the most abundant immune cells present, showed two distinct developmental trajectories, one promoting and the other suppressing meningioma growth, with the MIF-CD74 interaction serving as the primary signaling pathway for MIF signals in the tumor environment." (PMID 37880655, 2023). "Consequently, MIF expression is increased in hypoxic environments, such as those present within a tumor, depending on HIF-1α." (PMID 36672343, 2023). "In a tumor context, MIF may promote the migration of neutrophils into the tumor which, in turn, may promote cancer progression." (PMID 36672343, 2023). "First, to determine whether MIF from tumor cells or CD36+ CAFs mediates the regulation of CD33+ MDSC expansion, human or murine CD36+ CAFs were isolated from primary human HBV-related or murine HCC tumors." (PMID 36878933, 2023). "However, no relevant communication between HCC cells and adjacent non-tumor hepatocytes has been found in MIF signaling." (PMID 37842089, 2023). "In addition to a reduced tumor growth and proliferation of MIF knockdown cells, the expression levels of keratinocyte chemoattractant (KC) and VEGF were also significantly reduced in the ascites of this group of mice." (PMID 36672343, 2023). "Both haplotypes may lead to an overexpression of the MIF gene and a subsequent increase in plasmatic levels which might promote tumor growth and protects cancer cells from immunogenic cell death and other antitumor immune responses." (PMID 37485818, 2023). "Consistent with the described role of MIF as a cytokine promoting tumorigenesis via increasing tumor-promoting angiogenesis and vascular permeability, we observed reduced neoangiogenesis and reduced intravasation of tumor cells upon treatment with ON203." (PMID 37067909, 2023). "The protumor effects of MIF and APP have been reported in several studies, and their potential association with PCs may explain the additional mechanisms of tumor progression." (PMID 37138324, 2023). "A more direct link between MIF and angiogenesis was demonstrated by the group of R. Bucala, who showed that the administration of an anti-MIF monoclonal antibody to B-lymphoma tumor-bearing mice significantly reduced the tumor vascularization compared with the group receiving an isotype control." (PMID 36672343, 2023). "Furthermore, our data show that while tumor-derived MIF mostly acts in a paracrine manner on the BM microenvironment, MK also acts in an autocrine fashion on NB cells." (PMID 37365178, 2023). "Previous studies have reported that MIF promotes tumour cell proliferation and migration." (PMID 37784249, 2023). "Furthermore, a significant reduction in metastasis was observed in a metastatic mice model co-treated with UM exosomes and a MIF inhibitor compared to mice only treated with UM exosomes, highlighting the vital role of MIF in UM tumor metastasis." (PMID 37981907, 2023). "The results showed that MIF inhibitors significantly inhibited tumor growth." (PMID 37649598, 2023).
tumor (continued). "Moreover, MIF is often overexpressed in tumor tissue from numerous cancer indications, which has been associated with higher tumor burden and grade, increased metastasis risk, and poor prognosis." (PMID 37067909, 2023). "Besides, MIF-(CD74+CXCR4) and MIF-(CD74+CD44) pathways were widespread and are associated with multiple cell types in the tumor and normal tissues." (PMID 37335089, 2023). "The implication of macrophages in supporting tumor proliferation has been also demonstrated in HL and secretion of macrophage migration inhibitory factor (MIF) may contribute to the proliferation of HRS-cells." (PMID 36362802, 2022). "A reason for this discrepancy could be a potential pleiotropic effect that MIF might have depending on its cellular localization and tumour stage and type." (PMID 35012533, 2022). "MIF is involved in multiple pathophysiological processes such as inhibiting the migration of activated macrophages, activating lymphocytes, killing tumor cells, inducing macrophages to secrete a variety of proinflammatory factors, and inhibiting the anti-inflammatory effect of glucocorticoids." (PMID 35815289, 2022). "Studies in cancer show that MIF supports tumor progression via different mechanisms." (PMID 36496973, 2022). "Although this study included macrophages (bone marrow‐derived macrophages), we did not examine MIF‐mediated tumour inflammation or tumour‐associated macrophages." (PMID 35060345, 2022). "Then cytokines such as the macrophage colony-stimulating factor and macrophage migration inhibitory factor (MIF) are recruited and infiltrate into tumor tissues, and macrophage inflammatory protein 1α causes, differentiation of macrophages into TAM under the influence of the TME." (PMID 35874739, 2022). "We thus explored if MIF inhibition could impair NB cell tumor growth in vivo using LAN-1 xenograft models in athymic nude mice." (PMID 35715791, 2022). "In addition to direct effects, MIF is reported to facilitate tumor progression by enhancing angiogenesis and chemotherapy resistance." (PMID 35842634, 2022). "Tumor-derived MIF has an inhibitory effect on the activation and proliferation of T cells." (PMID 36551288, 2022). "MIF promotes the secretion of the inflammatory factor IL-6 in the hypoxic tumour microenvironment." (PMID 36042480, 2022). "With regard to discrepant results between in vivo and in vitro, we speculate that this may be due to the complex society of the tumour microenvironment in vivo, disturbing the prosurvival role of MIF." (PMID 36703790, 2022). "Levels of MIF expression were examined using immunohistochemical techniques, and staining scores were graded as weakly positive (5-49%) and strongly positive (>50%) based on the percentage of positively stained tumour cells." (PMID 36703790, 2022). "Meanwhile, stress conditions (e.g., hypoxia) and cytokines (including tumor-derived MIF) in TME could induce TA-MSCs to secrete high levels of MIF, leading to upregulation of MIF in tumor cells that affects TA-MSCs function." (PMID 35842634, 2022). "CD74 has been reported to promote tumor cell growth through interaction with MIF." (PMID 35169832, 2022). "A close relationship between MIF and tumor drug resistance has been established." (PMID 35842634, 2022). "Furthermore, co-expression of MIF and its receptor CD74 in NSCLC is associated with greater tumor angiogenesis and angiogenic CXC chemokine levels." (PMID 35842634, 2022). "Therefore, elevated MIF not only suppresses immune surveillance and anti-tumor immune responses and promotes tumor growth, but also favors cancer cell survival against anticancer drugs." (PMID 35372081, 2022). "The crucial role of the proinflammatory factor MIF in the tumour microenvironment and tumour immunity is hence speculated." (PMID 35060345, 2022).
tumor (continued). "The cytokines mainly mediated the intercellular communication among the three subtypes of malignant epithelial cells in the MK and MIF signaling pathway, which are involved in the inflammatory response, tumor growth, and cell migration, which have been poorly studied in GC." (PMID 36010627, 2022). "In addition, TA-MSCs secrete and transfer MIF to tumor cells via EVs, which directly activates the signaling pathways related to tumor progression." (PMID 35842634, 2022). "MIF is a pro-inflammatory cytokine that functions as a critical molecule in the innate immune system and involves in carcinogenesis, cancer cell proliferation, invasion, metastasis, angiogenesis, and drug resistance, and dampens the anti-tumor immune response." (PMID 35372081, 2022). "Similar mechanisms have also been found in MIF and tumor-related studies." (PMID 35842634, 2022). "It was found that MIF levels are significantly increased in tumour tissues, indicating that MIF may be an important tumour‐promoting factor." (PMID 35567291, 2022). "Also, CD74 promotes tumor cell survival by interacting with macrophage migration inhibitory factor (MIF)." (PMID 35784460, 2022). "In view of the similarities in their effects and mechanisms of action, we speculate that TA-MSCs, TA-MSCs-EVs and MIF act cooperatively to promote tumor progression." (PMID 35842634, 2022). "Collectively, these results indicated that the MIF-involved suppression of tumour growth may be due to its anti-apoptosis role." (PMID 36703790, 2022). "TA-MSCs transport MIF to tumor cells via EVs, facilitating tumor development." (PMID 35842634, 2022). "MIF may be involved in various physiological and pathological processes of the body, including inflammatory response, immune response, tumor genesis, and tissue damage and repair." (PMID 36186991, 2022). "Finally, MIF signaling induces the activation and secretion of pro-tumorigenic cytokines to support tumor growth." (PMID 36496973, 2022). "Similar with TA-MSCs and TA-MSCs-EVs, MIF can also activate multiple signaling pathways via binding to different receptors on the tumor cell surface and affects the expression of a range of downstream proteins and genes, in turn, influencing the proliferation, migration and invasion of tumors." (PMID 35842634, 2022). "After binding to target cell surface receptors, MIF could directly promote tumor cell proliferation, migration and invasion by activating downstream signaling pathways." (PMID 35842634, 2022). "A decrease in MIF in mouse BC tissue results in significant reduction of circulating MDSCs and its suppressive cytokines along with inhibition of growth and metastasis of BC in vivo, further indicating that MIF promotes tumor progression by regulating the number and function of MDSCs." (PMID 35842634, 2022). "These proposed pathways may explain the comparable tumor-promoting functions of MSCs, MSCs-EVs, and MIF." (PMID 35842634, 2022). "We thus hypothesized that MIF might be a potential tumor-secreted factor that has the capacity to act as a second signal in the setting of WGP-induced trained immunity." (PMID 35140221, 2022). "Notably, these molecules exert similar effects on tumor progression were similar, suggestive of potential interrelationships among MSCs, MSCs-EVs and MIF." (PMID 35842634, 2022). "On this basis, we hypothesized that TA-MSCs-EVs, the MIF axis, and TA-MSCs form a positive feedback loop with tumor cells, influencing the occurrence and development of tumors." (PMID 35842634, 2022). "TA-MSCs, TA-MSCs-EVs exert similar tumor-promoting effects via similar mechanisms as MIF." (PMID 35842634, 2022). "Later studies found that MIF can participate in a series of stress responses of the host to microbial infection; activate macrophages; inhibit migration; and enhance adhesion, phagocytosis, and tumor-killing activity." (PMID 36186991, 2022). "MIF transgenic mice have a corresponding increased tumor incidence." (PMID 36146458, 2022).